Y_RNA (Y RNA )
Gene: Miscellaneous RNA gene on chromosome 6 (17,737,458 to 17,737,556, reverse strand). Ensembl gene ENSG00000201442.
Homologues: Orthologues: chimpanzee Y_RNA (99% identical). Paralogues in human: Y_RNA (91% identical), RNY3 (90% identical), RNY3P1 (90% identical), Y_RNA (90% identical), Y_RNA (89% identical), Y_RNA (88% identical), RNY3P14 (87% identical), Y_RNA (87% identical), Y_RNA (86% identical), RNY3P11 (85% identical), RNY3P16 (85% identical), Y_RNA (85% identical), and 94 more.